MCAM (melanoma cell adhesion molecule)
Diseases named in the same sentence as MCAM in open-access papers (continued):
Sharing a sentence is not in itself a finding about the gene and the disease.
melanoma (continued). "Together, these results indicate that galectin-3 binding to the MCAM, which induces MCAM dimerization and clustering on the cell surface, activates downstream AKT signalling in melanoma cells." (PMID 36291660, 2022). "Melanoma cell adhesion molecule (MCAM, CD146, MUC18) is a heavily glycosylated transmembrane protein and a marker of melanoma metastasis." (PMID 36291660, 2022). "CD146 (alias MCAM, MUC18, and others) is also expressed on melanoma and leukemia cells and considered as an important marker for angiogenesis and cancer." (PMID 33868409, 2021). "A highly specific and sensitive multimarker RT-PCR assay based on the amplification (presence) of Tyr-OH, MART-1, MAGE-3, MUC-18/MCAM/CD146, and p97 transcripts was elaborated for analyzing 100 melanoma patients (AJCC stages I–IV)." (PMID 34830300, 2021). "Changes in melanoma chondroitin sulfate proteoglycan (MCSP), melanoma cell adhesion molecule (MCAM) and other proteins were documented in EVs from patient-derived melanoma cell lines and conformed in melanoma patients receiving targeted therapy." (PMID 33458258, 2021). "CD146 (cell surface glycoprotein MUC18; MCAM) is a well-known IgCAM member that plays an important role in melanoma progression and metastasis." (PMID 34439879, 2021). "MCAM, also known as MUC18 or CD146, is upregulated in tumors of neuroectodermal origin and is involved in melanoma cell metastasis." (PMID 34112916, 2021). "Expressions of melanoma cell adhesion molecule (MCAM) and metallothionein I and II were shown to be independent prognostic markers of prognosis in primary melanoma." (PMID 33915997, 2021). "Taken together, the silencing of MCAM radiosensitizes B16F10 melanoma and TS/A carcinoma, but the effect was more pronounced in melanoma than carcinoma." (PMID 32204304, 2020). "S100A8/S100A9 binds to the melanoma cell adhesion molecule (MCAM), a highly expressed cell adhesion molecule in melanoma." (PMID 32722137, 2020). "Melanoma cell-adhesion molecule (MCAM, also known as CD146) is the marker of antiaging and stemness and has been shown to gradually decrease after multiple passages of MSCs cultured from human umbilical cord blood." (PMID 32322277, 2020). "All tested antibodies, other than anti-MCAM and anti-MCSP, failed as relevant isolation tools for melanoma cells due to poor interaction with melanoma cells." (PMID 30735560, 2019). "Our data confirms that combined targeting of both MCAM and MCSP for melanoma CTC isolation using the IsoFlux CTC isolation platform improves cell isolation from cultured cells and patient blood samples." (PMID 30735560, 2019). "Related to melanoma, the melanoma cell adhesion molecule/MCAM/MUC18) was expressed from a SIN DNA plasmid (SIN-MUC18) and mice were vaccinated against B16F10 mouse melanoma cells." (PMID 30857255, 2019). "These markers include the two most commonly used melanoma surface markers for CTC enrichment, CSPG4 and MCAM." (PMID 31671846, 2019). "CD146, also known as melanoma cell adhesion molecule (MCAM, M-CAM and MUC18), was first described in malignant melanomas as a cell adhesion molecule." (PMID 29734758, 2018). "It is known that CREB induces metastasis of melanoma via MMP2 and adhesion molecules such as MCAM/MUC18 and dominant-negative mutant CREB has been shown to suppress metastasis." (PMID 29285247, 2017). "RT-PCR documented mRNA expression in all the melanoma cell lines analyzed (WM115, WM266.4, and the positive controls M10 and M14) for VEGF, FGF2, CDH2, CDH5, MMP-2, MMP-9, and the two isoforms of MCAM/MUC18." (PMID 28107182, 2017). "In recent years, several melanoma-specific cell surface molecules have been suggested for melanoma cell enrichment, including melanoma chondroitin sulphate proteoglycan (MCSP), melanoma cell adhesion molecule (MCAM) or CD27120." (PMID 26815318, 2016).
melanoma (continued). "In this study, five different melanoma antigens, MAGEA4, MAGEA10, MART1, TRP1 and MCAM, were incorporated into the VLPs and their localization within the particles was determined." (PMID 27403717, 2016). "All five melanoma antigens, the MART1, TRP1, MCAM, MAGEA4 and MAGEA10 proteins were detected in respective VLP’s confirming once again the effective incorporation of recombinant proteins into VLPs induced by overexpression of the MLV Gag protein." (PMID 27403717, 2016). "Five different melanoma antigens, MAGEA4, MAGEA10, MART1, TRP1 and MCAM, were co-expressed with the MLV Gag protein in mouse fibroblast cells, and their incorporation into VLPs and localization within the particles were determined." (PMID 27403717, 2016). "PAR-1 also promotes expression of melanoma cell adhesion molecule MCAM/MUC18 (MUC18), which is a key marker of melanoma metastasis." (PMID 26573921, 2015). "A reciprocal relationship between MCAM expression and AKT phosphorylation in melanoma cells has been suggested." (PMID 26703751, 2015). "Mcam (melanoma cell adhesion molecule/CD146), which was originally identified in human melanoma cells, has been extensively studied in tumors." (PMID 25826454, 2015). "Considering only thin melanomas (<1 mm thickness), one out of 14 cases was intensively MCAM/MUC18 positive (UPN13)." (PMID 24902661, 2014). "Like MCAM, CSPG4 is widely expressed on melanoma cells, appearing on >85% of cutaneous melanoma lesions and melanoma cell lines." (PMID 24069584, 2013). "They showed that PAX3 promoted a less differentiated, stem-like (via HES1, SOX9, NES, DCT), motile (via MCAM, CSPG4, and CXCR4) phenotype, characteristic of melanomas with high metastatic potential." (PMID 24069584, 2013). "Melanoma cell adhesion molecule (CD146, Muc18, S-Endo-1) is a cell surface glycoprotein belonging to the immunoglobulin (Ig) superfamily." (PMID 24069584, 2013). "Expression of MCAM, MCSP, ABCB5, CD271 and CD45 was demonstrated in A2058 melanoma cells by immunofluorescence." (PMID 22978632, 2012). "Forced expression of MCAM in MCAM-negative melanoma cells led to a significant increase in MMP-2 expression, and inhibition of MCAM using blocking antibodies decreased the expression of MMP-2." (PMID 22272201, 2012). "In melanoma cells, phosphatidylinositol 3 kinase (PI3K) was found to upregulate MCAM expression via AKT expression and over-expression of MCAM also activated endogenous AKT." (PMID 22272201, 2012). "Upregulation of AP-2α expression following CREB silencing increases endogenous p21Waf1 and decreases MCAM/MUC18, both known to be downstream target genes of AP-2α involved in melanoma progression." (PMID 20805990, 2010). "Several factors involved in melanoma invasion, resistance to apoptosis and proliferation, such as MMP-2, MCAM/MUC18, BCL-2 and TGF-α are regulated by both CREB and AP-2α, albeit in an opposite manner." (PMID 20805990, 2010). "The translated MCAM protein likely becomes highly stable through glycosylation mediated by glucosaminyl (N-acetyl) transferase 3, mucin type (GCNT3), which we previously reported in melanoma; notably, GCNT3 is also highly expressed in GC." (PMID 40924339, 2025). "Due to the abundant expression of MCAM already in many primary lesions, our data do not support the role of MCAM mRNA or protein expression levels as a biomarker for melanoma progression." (PMID 39945026, 2025). "Furthermore, treatment with s-MCAM upregulated the expression of EMT markers in two highly invasive human MCAM+ cancer cell lines—HEY (ovarian) and A375 (melanoma)." (PMID 41388158, 2025). "As previously reported, MCAM was not expressed on epidermal melanocytes but on many melanoma cells with high intra‐ and intertumoral heterogeneity." (PMID 39945026, 2025). "Initially, MCAM was described as a tumour antigen expressed in primary melanomas but not benign melanocytic nevi." (PMID 39945026, 2025).
melanoma (continued). "Furthermore, interactions between melanoma cell adhesion molecule (melanoma cell adhesion molecule [MCAM, also termed MUC18 or CD146]) on tumour surfaces and neutrophil-derived IL-8 promote melanoma proliferation, angiogenesis, and metastasis." (PMID 41451221, 2025). "Furthermore, RAGE and MCAM have also been reported to bind to S100A8/A9 protein heterodimers, mediating signaling in malignant melanoma." (PMID 41294858, 2025). "Notably, we identified differentially expressed cell surface markers including MCAM (CD146), CSPG4, and ITGA6/ITGA7, which are well-established melanoma resistance markers." (PMID 41000875, 2025). "We identified the melanoma cell adhesion molecule (MCAM/MUC18/CD146) and the ATP binding cassette subfamily B member 5 (ABCB5) as melanoma-specific targets to isolate and purify a highly primitive and aggressive subset of circulating melanoma cells (CMCs)." (PMID 40332096, 2025). "Among the upregulated candidates in plasma-derived EVs were melanoma markers, such as MCAM, TNC, and TGFBI, which were not regulated in depleted plasma samples." (PMID 38353833, 2024). "CTC detection technologies are dependent on a number of melanoma cell adhesion molecules, which are highly specific molecular markers for melanoma and include HMW-MAA,62,64 MART-1,65,66 CD146,67,68 and MAGE A.66,67,69–71 Melanoma is a kind of skin cancer that starts in melanocytes." (PMID 39218931, 2024). "In this study, we tested whether circ_0079593 is involved in the progression of melanoma aggressiveness by regulating CHAF1B and MCAM via the inhibition of miR-516b-5p." (PMID 39766913, 2024). "Melanoma cell adhesion molecules (MCAM/MUC18) are unique to metastatic melanoma and not present in normal melanocytes." (PMID 37366925, 2023). "Furthermore, circulating melanoma cells have been described to interact with perivascular MSCs through CXCR4/CXCL12 signaling and melanoma cell adhesion molecule (MCAM, CD146) in vivo, an interaction shown to be required for BM invasion." (PMID 33287630, 2021). "However, melanoma cells can be detected in single cell suspensions of tumor tissue, by combinations of ICAM-1, MUC18/MCAM (CD146) and the exclusion of CD45." (PMID 34910301, 2021). "When applying multiparametric flow cytometry, it was also presented that CMCs detected based on the limited expression of MCAM, MCSP, ABCB5, receptor activator of NF-κB (RANK), and CD271 markers were far more abundant in melanoma, especially in late-stage patients in comparison to healthy controls." (PMID 34575876, 2021). "Melanoma cell adhesion molecule (MCAM; CD146, MUC18) is an integral membrane glycoprotein of the immunoglobulin gene superfamily, which initially has been described in the context of cancer metastasis and tissue invasiveness of melanoma." (PMID 33381120, 2020). "MCAM and EMMPRIN are both highly expressed in melanoma and inhibition of the interaction between these receptors and S100A8/A9 could suppress lung metastasis in vivo, thereby representing an interesting target for therapeutic approaches." (PMID 32722137, 2020). "Moreover, WNT5A induces depalmitoylation of melanoma cell adhesion molecule (MCAM) and, subsequently, polarizes localization of MCAM and CD44 (another cell adhesion molecule) to promote directional movement and invasion of melanoma cells." (PMID 30166456, 2018). "Due to decreased melanoma invasion in collagen observed in APT1SA expressing cells, we hypothesize that the decreased depalmitoylation of MCAM may play a role in the APT1 mediated invasion." (PMID 29648538, 2018). "CD44 levels are elevated in multiple cancer types and MCAM is expressed in melanoma cells and not untransformed melanocytes." (PMID 29648538, 2018). "MCAM/MUC18/CD146 behaves as a ‘molecular warning of progression’ and its targeting could constitute an innovative therapeutic strategy for the CD146-positive melanoma." (PMID 28280601, 2017).
melanoma (continued). "Specific melanoma antigens, in particular MCAM (MUC18/MelCAM/CD146), could be a potentially useful tool to isolate CMCs as well as be a prognostic, predictive biomarker." (PMID 28280601, 2017). "Indeed, given the difficulty of isolating whole CMCs, MCAM/MUC18/MelCAM/CD146 has been proposed as a substitute for EpCAM in immuno-targeting and separation of melanoma cells using positive selection." (PMID 28280601, 2017). "MCAM/MUC18/CD146 was significantly more common in non-surgically treated advanced melanoma patients with a negative outcome than in those with a positive outcome (43 versus 9%), reasonably due to an ineffective eradication of CMCs." (PMID 28280601, 2017). "None of the melanoma antigens, except for the MCAM protein, were exposed on the cell surface of fibroblasts expressing the melanoma antigens and MLV Gag protein." (PMID 27403717, 2016). "MCAM/MUC18, a melanoma cell adhesion molecule, is recently obtaining more attention as a novel biomarker for disease progression and poor outcome in patients affected by melanoma." (PMID 24902661, 2014). "The interaction of MCAM with VEGFR-2 on melanoma cells remains to be confirmed, although it is known melanoma express VEGF and VEGFR-2, and overexpression of VEGF-A in a melanoma cell line with VEGFR-2 favored cell growth and survival through MAPK and PI3K signaling pathways." (PMID 24069584, 2013). "The fact that the majority of metastatic melanoma express these stem cell markers, and when present, neither MCAM or CSPG4 is expressed by a minor population of cells within the melanoma leads one to think about rare cancer stem cells in melanoma." (PMID 24069584, 2013). "There is also evidence that MCAM expression facilitates melanoma-endothelial cell adhesion although it is not known if this is mediated via carbohydrate or protein binding." (PMID 22272201, 2012). "In melanoma, inactivation of CREB by dominant-negative KCREB reduced tumor growth and experimental lung metastasis by acting as a survival factor and regulating the expression and activity of MMP-2 and the adhesion molecule MCAM/MUC18." (PMID 20805990, 2010). "CD146 (also referred to as MUC18, MCAM, Mel-CAM, S-Endo-1, P1H12 antigen) was initially identified as a marker of tumour progression and metastasis formation in human melanoma." (PMID 16160694, 2005). "Our study confirmed the antiproliferative effect of MCAM silencing in tumor cells that have high-level (B16F10 melanoma) and low-level (TS/A carcinoma) expressions of MCAM, since silencing MCAM after GET reduced cell survival (the clonogenicity) by 85% in melanoma and 43% carcinoma." (PMID 32204304, 2020). "Although some of the correlating target cell surface markers may still be expressed in some melanoma cells, since our data supports careful rationalisation of isolation antibodies, we consider targeting both MCAM and MCSP is the most viable immunomagnetic melanoma CTC isolation strategy." (PMID 30735560, 2019). "METCAM/MUC18 was first discovered to be profoundly expressed on the cellular surface of the majority of malignant human melanomas (thus named as MUC18) and suggested to play a central role in the progression of human melanoma (thus was originally named as MCAM and Mel-CAM)." (PMID 30274262, 2018). "Taken together, MCAM/MUC18/CD146 molecular expression analysis, sequential monitoring of the transcripts and detection of the soluble form could help to investigate or follow the melanoma remission or progression even in apparent disease-free status." (PMID 28280601, 2017). "Moreover, differential expression of melanoma epithelial cell adhesion molecule (MCAM) by other non-melanoma cells such as vascular endothelial cells, smooth muscle cells and pericytes makes it less reliable for melanoma cell isolation." (PMID 26815318, 2016).
melanoma (continued). "If the achievement of MCAM/MUC18 positivity is transitory, patients should not develop progression of melanoma disease; on the contrary, when persistent, patients could be at an increased risk of recurrence." (PMID 24902661, 2014). "Melanoma cell adhesion molecule (MCAM/cd146/MUC18) is a component of a “Wnt-Receptor-Actin-Myosin-Polarity (W-RAMP)” structure that mediates polarity and protrusion retraction, and was previously identified on a uropod-like structure for WM239a melanoma cells in synthetic ECM." (PMID 24349113, 2013). "It is now well known that up- or downregulation of several adhesion molecules, such as N- and E-cadherin, MCAM (melanoma cell adhesion molecule), VCAM (vascular cell adhesion molecule), integrins, can be involved in the progression of several cancer types, including melanoma." (PMID 22929570, 2012). "Notably, melanoma cells can express receptors for calprotectin, including RAGE (Receptor for Advanced Glycation End-Products), EMMPRIN (Extracellular Matrix Metalloproteinase Inducer, also known as Basigin or CD147), TLR4 (Toll-like receptor 4), and MCAM (Melanoma Cell Adhesion Molecule, CD146)." (PMID 40869349, 2025). "Interestingly,statistical analyses revealed that in primary melanoma, simultaneousexpression occurs more frequently when compared to the metastaticmodels (88% vs 60%) but any specific correlation was not identifiedamong tested subgroups including CD44 + vimentin, CD44 + MCAM, andvimentin + MCAM." (PMID 40621031, 2025). "In this patient the BRAF V600E mutation was identified in sorted CD146+/MCAM+/CD45− cells, whilst the mutation was not identified in sorted leukocytes (MCAM−/MCSP−/CD45+ cells) from the same specimen, confirming that MCAM+/MCSP+ cells identified by FCM indeed represent true melanoma cells." (PMID 38790134, 2024). "However, at that time, we could not define the expression level of MCAM protein in mouse melanoma cell lines in comparison to their normal counterparts." (PMID 30899801, 2019). "We also tested the modulators of the EMT pathway (spectralflow cytometry of vimentin and MCAM and CD44 expression) to figureout differences between BRAF and non-BRAF positive melanoma cell linesusing large tumorspheres." (PMID 40621031, 2025). "Downstream signaling analyses showed that MCAM drives the activation of ETV4, which in turn modulates the expression and activity of ZEB1 but not MMP25 observed in melanoma." (PMID 40924339, 2025). "Among the candidates obtained, MCAM and CHAF1B were found to be the most significantly overexpressed genes in melanoma metastasis cells, along with no miR-516b-5p levels (LM-16) and with high miR-516b-5p levels in LM-36." (PMID 39766913, 2024). "Cohesion between melanoma cells is mediated by N-cadherin, αvβ3-integrin, L1-CAM, AL-CAM and MCAM/MUC18 that are not expressed on melanocytes." (PMID 33870460, 2021). "CD146/MCAM expression increases gradually with melanoma progression and has been shown to be higher in metastatic melanoma cells than in nonmetastatic melanoma cells." (PMID 33969605, 2021). "In migrating melanoma cells non-canonical WNT signalling leads to cytoskeletal rearrangement and asymmetric distribution of MCAM (melanoma cell adhesion molecule, CD146) through its controlled endocytosis." (PMID 28923978, 2017). "Moreover, in our experience, the detection of MCAM/MUC18 transcripts only in a small subset of patients—twenty-two out of 175 melanoma patients—does not fit the hypothesis of a possible overestimation, leading to regard our finding as an expression of a real biological status related to melanoma." (PMID 24902661, 2014). "Furthermore, known melanoma markers, such as MCAM, TNC, and TGFBI, were upregulated in melanoma EVs but not in depleted melanoma plasma, highlighting the specific information contained in EVs." (PMID 38353833, 2024).